EZH2 (enhancer of zeste 2 polycomb repressive complex 2 subunit)
Diseases named in the same sentence as EZH2 in open-access papers (continued):
Sharing a sentence is not in itself a finding about the gene and the disease.
gastric cancer (254 papers, 2010 to 2026). A primary or metastatic malignant neoplasm involving the stomach. "Specifically, NEAT1 can function as a scaffold by interacting with EZH2 to regulate the expression of EZH2 downstream genes, of which dysregulation is associated with invasion and metastasis of gastric cancer cells." (PMID 37365581, 2023). "In conclusion, gene polymorphisms in EZH2 play a crucial role in the occurrence and development of gastric cancer." (PMID 36672374, 2023). "The high EZH2 expression within invasive tissues of gastric carcinoma was linked with the invasive depth and metastasis of lymph nodes." (PMID 38048186, 2023). "A similar phenomenon occurs in gastric cancer with lncRNA urothelial cancer-associated 1 (UCA1) which binds to EZH2 and induces the down-regulation of tumor-suppressor factors including p21 and Sprouty RTK signaling antagonist 1 (SPRY1)." (PMID 35236381, 2022). "In intestinal gastric cancer, the loss of microRNA-101 can lead to E-cadherin functional downregulation through EZH2 up-regulation." (PMID 34422902, 2021). "Herein, hyperactivation of STAT-3 has been associated with enhanced EZH2 expression resulting in a poor prognosis of multiple cancers types like gastric carcinoma." (PMID 35127527, 2021). "The influences of oncogenic Ezh2 on the progression and prognosis of gastric cancer (GC) and the underlying mechanisms are still poorly understood." (PMID 29335012, 2018). "Here, we used RNA immunoprecipitation sequencing (RIP-seq) to profile EZH2-associated transcripts in human gastric cancer cell lines." (PMID 26871474, 2016). "In this study, we modified a previous RIP-seq method to identify EZH2-associated RNAs in gastric cancer cells." (PMID 26871474, 2016). "Further, we found that EZH2 was associated with pN stage and T status in gastric cancer, and with differentiation in NSCLC." (PMID 25974088, 2015). "Some miRNAs frequently associated to EZH2 regulation in several tumor types, such as bladder and gastric cancer, hepatocellular carcinoma and neuronal differentiation, include miR-214, miR-124 and miR-137." (PMID 26580594, 2015). "In many tumor types, such as prostate, breast, bladder, and gastric cancer, EZH2 levels are elevated in cancer tissues and associated with poor prognosis." (PMID 24312307, 2013). "EZH2 has also been implicated in multidrug resistance in gastric cancer and ovarian cancer." (PMID 34564701, 2021). "Polymorphisms (rs12670401 and rs6464926) of EZH2 were identified to be significantly associated with the risk of gastric cancer and C allele of EZH2 rs12670401 and T allele of EZH2 rs6464926 showed strong associations with increased gastric cancer susceptibility." (PMID 29089464, 2018). "Additionally, increased sensitivity of ARID1A-deficient cancer cells to treatment with small molecule inhibitor of the PI3K/AKT pathway or selective sensitivity of EZH2 inhibitors against ARID1A-deficient gastric cancer could be demonstrated." (PMID 34359794, 2021). "Meanwhile, p21, a well-known cell cycle inhibitor, was proved to be down-regulated by EZH2 to proliferate gastric cancer cells." (PMID 40028035, 2025). "As a transcriptional factor, STAT3 has been reported to upregulate EZH2 expression and associate with advanced TNM stage and poor prognosis in gastric cancer." (PMID 39917394, 2025). "Elevated NEAT1 then acts as a scaffold, influencing the expression of EZH2 and consequently promoting the invasion and metastasis of gastric cancer (GC) cells." (PMID 40384875, 2025). "For instance, TEAD4-activated MNX1-AS1 has been shown to facilitate gastric cancer progression through the EZH2/BTG2 and miR-6785-5p/BCL2 axes." (PMID 39735666, 2025). "Further, RNA pull-down using biotinylated SNHG22 and nuclear protein extracts from gastric cancer cells followed by mass spectrometry analysis of enriched proteins showed that SNHG22 directly interacts with EZH2." (PMID 38473229, 2024).
gastric cancer (continued). "LINC00337 acts as an oncogenic lncRNA via its effect on EZH2, to repress p21 and promote gastric cancer cell proliferation, and through the miR-1285/YTHDF1 axis, to promote the progression of lung adenocarcinoma." (PMID 38279317, 2024). "Gan and collaborators found that EZH2 is capable of initiating an epithelial–mesenchymal transition in gastric cancer cells by influencing the Akt/PTEN axis." (PMID 39457484, 2024). "BMP2 is associated with the occurrence of various cancers and can inhibit the proliferation of gastric cancer cells by downregulating EZH2." (PMID 37570275, 2023). "For example, LINC00152 is known to mediate the infiltration of CD8 T cells by interacting with EZH2, thereby affecting the progression of gastric cancer." (PMID 37415739, 2023). "The Enhancer of Zeste Homolog 2 (EZH2), functioning as a polycomb protein, also upregulates Cyclin E in gastric cancer cells, as its inhibition leads to Cyclin D1 and Cyclin E downregulation." (PMID 36769170, 2023). "We aim to present the value of EZH2 research in gastric cancer by focusing on the crucial events of EZH2 involvement in gastric cancer progression." (PMID 36672374, 2023). "It has been found that EZH2 is overexpressed in the stomach, which promotes the progression of gastric cancer through multiple pathways." (PMID 36672374, 2023). "Relevant studies have found that EZH2 is significantly overexpressed in lymphoid malignancies, gastric cancer, and uveal melanoma." (PMID 37988356, 2023). "On the other hand, EZH2 silencing upregulates tumor-suppressor factors such as p15, p21, p27 and miRNA-218 that can in turn suppress the progression of lung and gastric cancers and enhance their sensitivity to cisplatin chemotherapy." (PMID 35236381, 2022). "The LncRNA UCA1, which is upregulated in gastric cancers, recruits EZH2 (enhancer of zeste homolog 2) to the promoters of the genes that encode p27 (CDKN1B) and the sprouty RTK signaling antagonist 1 (SPRY1) to mediate the repressive H3K27me3-trimethylation." (PMID 36010595, 2022). "A recent experiment uses lentivirus for delivery of miRNA-124 to down-regulate EZH2 expression and successfully inhibit to gastric cancer progression." (PMID 35236381, 2022). "More evidence shows that EZH2 is strongly denoted in numerous tumors, including esophageal cancer, gastric cancer, and endometrial carcinoma, which also contains BC." (PMID 36712863, 2022). "The lncRNA metastasis-associated lung adenocarcinoma transcript 1 (MALAT1) can promote gastric cancer progression via reducing miRNA-124-3p expression and subsequent induction of EZH2 signaling." (PMID 35236381, 2022). "STAT3 and p-STAT3 are significantly increased in gastric cancer tissues, which affect the prognosis of patients by regulating the transcriptional activity of downstream factors EZH2." (PMID 36225196, 2022). "It has been reported that exposing gastric cancer cells to hydrogen is associated with down-regulation of MALAT1, and subsequent upregulation of miRNA-124-3p as a tumor-suppressor, resulting in EZH2 inhibition and suppression of proliferation and invasion." (PMID 35236381, 2022). "As previous reported, lncRNA SNHG17 was also demonstrated to facilitate gastric cancer progression through the inhibition of p15 and p57 by directly binding to EZH2." (PMID 35902569, 2022). "In a recent study, the authors showed that lncRNA UCA1 promoted the cisplatin resistance of MKN45 and MGC803 gastric cancer cells by recruiting EZH2, activating the PI3K/AKT pathway, and inhibiting cisplatin-induced apoptosis." (PMID 36230683, 2022). "An increasing number of studies have revealed that EZH2 is abnormally expressed in numerous tumors, including liver cancer, gastric cancer, and breast cancer, and correlates with tumor progression, metastasis, and drug resistance in prostate cancer cells." (PMID 35627262, 2022).
gastric cancer (continued). "EZH2 down-regulation, on the other hand, leads to inhibition of gastric cancer progression, and promotion of sensitivity to 5-fluorouracil chemotherapy." (PMID 35236381, 2022). "Another study showed that by demethylating H3K27me3 marks in CAFs, pro-inflammatory cytokine-driven EZH2 downregulation maintains the senescence-associated secretory phenotype and promotes peritoneal tumor progression of gastric cancer (GC) via JAK-STAT signaling." (PMID 36358967, 2022). "Increasing evidence has addressed the role of EZH2 in different human malignancies, including ovarian cancer, pancreatic cancer, gastric cancer, and even HCC." (PMID 35627262, 2022). "Silencing EZH2 through siRNA reversed cisplatin resistance in cisplatin-resistant AGS/DDP gastric cancer cells." (PMID 36230683, 2022). "In gastric cancer SNHG22 LncRNA recruits EZH2 and sponge mir-200c-3p to suppress tumor suppressor genes and promote the cancer progression." (PMID 36316365, 2022). "While the downstream mechanisms of this action still need to be elucidated, the mechanisms that converge on EZH2 in gastric cancer cisplatin resistance have been more explored." (PMID 36230683, 2022). "For instance, MNX1-AS1 overexpression promotes gastric cancer progression via the EZH2/BTG2 and miR-6785-5p/BCL2 axis." (PMID 33882027, 2021). "DNMT1- and EZH2-mediated methylation contributes to the progression of gastric cancer and glioblastoma." (PMID 33743723, 2021). "It is interesting to note that Jie and colleagues reported that EZH2 substantially impedes CDKN2B activation, which contributes to cellular senescence triggered by EZH2 depletion in gastric cancer cells." (PMID 33664859, 2021). "H2 gas significantly inhibited gastric tumor growth in vivo and the proliferation, migration, and lncRNA MALAT1 and EZH2 expression of gastric cancer cells while upregulated miR-124-3p expression." (PMID 33482814, 2021). "MiR-124-3p mimics abrogated lncRNA MALAT1 promoted EZH2 expression and gastric cancer cell proliferation and migration." (PMID 33482814, 2021). "HOTAIR has been found to be upregulated in gastric cancer, and can promote tumor metastasis by binding to EZH2 with the E-cadherin promoter." (PMID 34422902, 2021). "The current study demonstrated that lncRNA MALAT1 promoted gastric cancer proliferation and migration through modulating miR-124-3p/EZH2 axis." (PMID 33482814, 2021). "In gastric cancer, the ectopic expression of miR-101 significantly inhibits cell proliferation, migration and invasion by targeting enhancer of zeste homolog 2 (EZH2), Cyclooxygenase-2 (COX-2), Myeloid cell leukemia-1 (MCL-1) and Fos." (PMID 34659567, 2021). "H2 exposure drastically reduced gastric cancer growth in xenograft mouse model and inhibited EZH2 expression in cancer tissue, which was enhanced by miR-124-3p and suppressed by lncRNA MALAT1." (PMID 33482814, 2021). "For example, miR-101 decreases the invasion and migration ability of several tumor types, including osteosarcoma in vitro and gastric cancer and glioblastoma in vitro and in vivo, through the post-transcriptional downregulation of EZH2." (PMID 34811354, 2021). "H2 gas inhibited the proliferation and migration of MGC-803 and BGC-823 gastric cancer cells and downregulated the expression of lncRNA MALAT1and EZH2." (PMID 33482814, 2021). "For example, UCA1 promotes gastric cancer cell proliferation by activation of AKT via recruiting EZH2." (PMID 34809621, 2021). "For instance, lncRNA UCA1 mediates the expression of p21 and SPRY1 through interacting with EZH2, thus facilitating tumour progression of gastric cancer." (PMID 33834618, 2021).
gastric cancer (continued). "For instance, SNHG3 promotes gastric cancer progression through regulating neighboring mediator subunit 18 (MED18) gene methylation by binding to enhancer of zeste homolog 2 (EZH2)." (PMID 33292213, 2020). "Studies involving the immunohistochemical evaluation of EZH2 expression in gastric cancer have revealed that EZH2 significantly correlates with poor prognosis." (PMID 33050946, 2020). "In gastric cancer, lncRNA UCA1 enhanced the translation of cyclin D1 via recruiting EZH2 and further precipitated the proliferation and cell cycle progression of gastric cancer." (PMID 32587476, 2020). "It was approved that SNHG6 played an oncogenic role in gastric cancer through silencing expression at a transcriptional level by recruiting enhancer of EZH2 to the promoter of p27." (PMID 32321469, 2020). "This study also revealed that TET family serving as a ceRNA significantly to enhance EZH2 expression by competitively binding to miR-26, thereby exerting carcinogenic effects on gastric cancer." (PMID 32014008, 2020). "In a cohort of 117 gastric cancer cases with corresponding normal tissues, 70.1% of tumor samples were positive for EZH2 when compared to 5.4% of benign gastric mucosa samples." (PMID 33050946, 2020). "STAT3 signaling drives transcription activation of EZH2 and mediates poor prognosis in gastric cancer." (PMID 32831016, 2020). "To elucidate the role of the LINC01303/miR‐101‐3p/EZH2 axis in gastric cancer, we performed experiments using the miR‐101‐3p inhibitor and EZH2 siRNA." (PMID 31497936, 2019). "Similar to the results in this study, EZH2 has been validated as a direct target of miR-217 in gastric cancer cells." (PMID 31695969, 2019). "lncRNA HOXA11-AS acts as a decoy for miR-1297, resulting in elevated expression of EZH2 in gastric cancer." (PMID 31752906, 2019). "Because the response to EZH2 inhibitors often correlates with EZH2 overexpression, we investigated EZH2 expression by IHC staining in gastric cancer." (PMID 31043675, 2019). "Studies have shown that lncRNAXIST was over-expressed in gastric cancer, which can be as a molecular sponge to modulate EZH2 expression by sponging miR-101 and it has been suggested possibly participating in the progression of gastric cancer." (PMID 29420609, 2018). "It was previously identified that PTEN/Akt signaling and Ezh2 are important regulators for the proliferation and invasion of gastric cancer cells." (PMID 29335012, 2018). "HOXA11-AS, associated with the cell cycle through E2F1, has been seen to promote gastric cancer proliferation and invasion (with EZH2) and can act as a “molecular sponge” for EZH2 by absorbing (via direct interaction) miR-1297." (PMID 29757368, 2018). "And also, Xist was up-regulated in gastric cancer and knockdown of Xist suppressed cell proliferation, migration and invasion through regulating lncRNA Xist/miR-101/EZH2 axis." (PMID 29254174, 2017). "LINC00152 overexpression facilitates gastric cancer cell proliferation through accelerating the cell cycle by binding to EZH2 and repressing p15 and p21 transcription." (PMID 27246976, 2017). "Long non-coding RNA HOXA-AS2 promotes gastric cancer proliferation by epigenetically silencing P21/PLK3/DDIT3 expression by binding with EZH2 (enhaner of zeste homolog 2)." (PMID 29221147, 2017). "LncRNA XIST can act as a molecular sponge of miR-101 to modulate EZH2 and thereby promotes the progression of gastric cancer." (PMID 27911852, 2017). "Several recent studies indicated that TUG1 regulate genes expression by binding with EZH2 to affect cell proliferation in human non-small cell lung cancer, gastric cancer and hepatocellular carcinoma." (PMID 28069000, 2017). "More recently, upregulation of XIST was reported to be associated with overexpression of EZH2, a key component of PRC2 and to act as an adverse prognosis indicator of gastric cancer patients." (PMID 29100288, 2017).
gastric cancer (continued). "Briefly, we performed a transcriptome-wide EZH2-RNAs interaction analysis in gastric cancer cells with a modified RIP-seq approach." (PMID 26871474, 2016). "Mastukawa and his colleagues were the first to report the role of EZH2 and its prognostic significance in gastric cancer." (PMID 27620004, 2016). "A previous study has described EZH2-activated Wnt/β-catenin signaling in gastric cancer and hepatocellular carcinoma." (PMID 27092879, 2016). "This is in accordance with our previous results that EZH2 is overexpressed and promotes tumor progression in gastric cancer." (PMID 27620004, 2016). "More recently, it has been shown that up-regulation of EZH2 contributes to gastric cancer invasion and metastasis." (PMID 27620004, 2016). "All reported the prognostic value of EZH2 status for survival in colorectal cancer or gastric cancer or oesophageal cancer patients." (PMID 26859127, 2016). "We compared the EZH2-bound transcripts among two gastric cancer cell lines and their normal counterpart." (PMID 26871474, 2016). "It is known that miRNAs function by targeting downstream genes, and EZH2 has been proved to be involved in gastric cancer progression." (PMID 27620004, 2016). "In gastric cancer, previous studies have demonstrated that down-regulation of miR-101 resulted in overexpression of EZH2 and promoted tumor progression." (PMID 27620004, 2016). "Further experiments revealed that EZH2 was a direct and functional target of miR-217 in gastric cancer cells." (PMID 25869101, 2015). "Based on a bioinformatic analysis, we found that EZH2 is a potential target of miR-217 and is involved in gastric cancer proliferation and invasion." (PMID 25869101, 2015). "EZH2 has been found to be overexpressed in multiple tumors, including those found in gastric cancer patients." (PMID 25869101, 2015). "We performed Western blotting and found that only the protein level of EZH2 was significantly reduced following the ectopic expression of miR-217 in gastric cancer cells." (PMID 25869101, 2015). "Knockdown of EZH2 mimicked the tumor-suppressive effects of miR-217 in gastric cancer cells, whereas the reintroduction of EZH2 abolished its effects." (PMID 25869101, 2015). "EZH2 mRNA levels also decreased following the overexpression of miR-217 in the gastric cancer cells." (PMID 25869101, 2015). "Further experiments revealed that Polycomb group protein enhancer of zeste homolog 2 (EZH2) was a direct target of miR-217 in gastric cancer cells." (PMID 25869101, 2015). "Overexpression of EZH2 is a marker of advanced and metastatic disease in numerous cancers, including bladder cancer, gastric cancer, lung cancer, cervical cancer and hepatocellular carcinoma." (PMID 25890171, 2015). "In this regard, the concerted action of DNMT1 and EZH2 mediates the repression of the miR-200a,b/429 locus contributing to the progression of gastric cancer and glioblastoma." (PMID 26580594, 2015). "The ectopic expression of miR-101 significantly inhibited cellular proliferation, migration, and invasion of gastric cancer cells by targeting EZH2, Cox-2, Mcl-1, and Fos." (PMID 23768087, 2013). "For example, the oncogenic lncRNA linc01503 in gastric cancer interacts with zeste homolog 2 (EZH2) and lysine (K)-specific demethylase 1A (LSD1) enhancers, targeting the promoter regions of dual-specificity phosphatase 5 (DUSP5) and cyclin-dependent kinase inhibitor 1A (CDKN1A)." (PMID 41229433, 2025). "EZH2, a histone lysine N-methyltransferase responsible for mediating histone methylation and transcriptional repression, plays a role in the resistance of gastric cancer cells to 5-fluorouracil (5-FU) by suppressing FBXO32 expression." (PMID 40534867, 2025). "We further analyzed in gastric cancer subtypes the expression of genes involved in epigenetic controls, such as EZH2 (Enhancer of zest homolog 2 involved in histone modifications), non-coding RNA (including long non-coding RNAs such as HOTAIR, H19) and DNMT1 (involved in DNA methylation)." (PMID 40868070, 2025).